DMTF1 (cyclin D binding myb like transcription factor 1)
Description:
Binds to the consensus sequence 5'-CCCG[GT]ATGT-3' (By similarity). Isoform 1 may cooperate with MYB to activate transcription of the ANPEP gene. Isoform 2 may antagonize transcriptional activation by isoform 1.
Synonyms: hDMP1; DMP1; DMTF; MRUL
Tractability: PROTAC: ubiquitination databases record sites on it.
Gene: Protein-coding gene on chromosome 7 (87,152,409 to 87,196,337, forward strand). Ensembl gene ENSG00000135164.
Subcellular location: Nucleus
Subcellular location (Human Protein Atlas): Nucleoplasm
Gene Ontology:
Molecular function: DNA-binding transcription factor activity; DNA-binding transcription factor activity, RNA polymerase II-specific; RNA polymerase II cis-regulatory region sequence-specific DNA binding
Biological process: regulation of DNA-templated transcription; regulation of transcription by RNA polymerase II
Cellular component: nucleoplasm; nucleus
Genetic constraint (gnomAD): Loss-of-function variants: 25 observed, 64.75 expected, observed/expected ratio (o/e) 0.39, 90% interval 0.28 to 0.54. The upper end of that interval is the gene's LOEUF score, 0.54, which puts it in group 2 of 6, group 1 being the genes least tolerant of losing a copy. Missense variants: 572 observed, 748.21 expected, observed/expected ratio (o/e) 0.76, 90% interval 0.71 to 0.82. Synonymous variants: 275 observed, 258.45 expected, observed/expected ratio (o/e) 1.06, 90% interval 0.96 to 1.18.
Homologues: Orthologues: macaque DMTF1 (99% identical), chimpanzee DMTF1 (99% identical), dog DMTF1 (97% identical), pig DMTF1 (97% identical), rabbit DMTF1 (96% identical), mouse Dmtf1 (95% identical), rat Dmtf1 (95% identical), guinea pig DMTF1 (93% identical), tropical clawed frog dmtf1 (69% identical), zebrafish dmtf1 (56% identical), rat Dmtf1l2 (39% identical), mouse Dmtf1l (39% identical). Paralogues in human: SNAPC4 (17% identical), MYB (14% identical), MYBL1 (14% identical), MYBL2 (12% identical), CDC5L (10% identical), TTF1 (7% identical).
Diseases named in the same sentence as DMTF1 in open-access papers:
DMTF1 is named in the same sentence as 20 diseases in open-access papers, as found by Europe PMC text mining. Sharing a sentence is not in itself a finding about the gene and the disease. The quoted sentences say what the papers report.
breast carcinoma (11 papers, 2013 to 2026). "Consistently, we recently demonstrated that DMTF1α inhibits EBRR2-induced mammary tumorigenesis and DMTF1 loss promotes breast cancer development mediated by CCND1 overexpression." (PMID 28257090, 2017). "As a result, we observed that alternative DMTF1 splicing and DMTF1β overexpression were associated with poor clinical outcomes, suggesting a potential diagnostic value of DMTF1β for breast cancer patients." (PMID 28257090, 2017). "Importantly, DMTF1 splicing favoring DMTF1β mRNA and protein overexpression was associated with poor clinical outcomes of breast cancer patients, strongly suggesting a biological function of DMTF1β during mammary tumorigenesis." (PMID 28257090, 2017). "Overall, our data strongly support the notion that DMTF1 alternative splicing is a driving mechanism utilized by cancer cells to promote breast cancer development and progression." (PMID 28257090, 2017). "We found that DMTF1 alternative splicing occurred in about 30% of breast cancer cases, with relatively decreased DMTF1α and increased DMTF1β expression." (PMID 28257090, 2017). "The human DMTF1 gene is located on chromosome 7p21, a region frequently deleted in breast cancer, acute myeloid leukemia (AML), and myelodysplastic syndrome (MDS)." (PMID 28257090, 2017). "Previously, DMTF1 was considered as a tumor suppressor by inducing cell cycle arrest in lung cancer and breast cancer." (PMID 25965824, 2015). "In contrast to previous studies showing that DMTF1 LOH or null promotes tumorigenesis in Eμ-myc–induced B cell lymphoma, K-rasLA lung cancer and MMTV-neu/Erbb2 breast cancer models, we now report a growth promoting function of DMTF1 in NSC." (PMID 41481722, 2026). "We recently demonstrated that an alternative cyclin D-binding myb-like transcription factor 1 (DMTF1) pre-mRNA splicing isoform, DMTF1β, is increasingly expressed in breast cancer and promotes mammary tumorigenesis in a transgenic mouse model." (PMID 28257090, 2017).
lung carcinoma (4 papers, 2008 to 2026). "In human lung carcinomas, DMTF1 loss of heterozygosity (LOH) at a frequency of ~35% has been reported, and DMTF1 LOH or null accelerates tumorigenesis in a K-RasLA lung cancer mouse model relative to the DMTF1 intact counterpart." (PMID 41481722, 2026). "In lung cancer, DMTF1 is considered as a pivotal tumor suppressor." (PMID 25965824, 2015).
bladder cancer (3 papers, 2015 to 2021). "The identification of miR-155 and its novel target DMTF1 will be valuable in developing diagnostic markers and therapeutic applications for bladder cancer." (PMID 25965824, 2015). "In bladder cancer, this miR is known to be significantly overexpressed, promoting tumour growth by repressing DMTF1, a tumour-supressing gene." (PMID 33806327, 2021). "A recent study also showed that miR-155 inhibited tumor suppressor DMTF1 expression in bladder cancer." (PMID 26967247, 2016). "Taken together with rescue experiment, it was confirmed that DMTF1 suppresses proliferation of bladder cancer cells." (PMID 25965824, 2015). "Taken together, our findings suggested that miR-155 functions as a tumor promoter in bladder cancer, which is partially through repressing DMTF1 expression." (PMID 25965824, 2015). "Taken together, this report suggested that miR-155 promotes bladder cancer growth by directly repressing the tumor suppressor DMTF1." (PMID 25965824, 2015). "In addition, clinical data showed that DMTF1 mRNA expression is significantly lower in bladder cancer tissues." (PMID 25965824, 2015). "In addition, we observed lower mRNA expression of DMTF1 in bladder cancer cell lines when compared to that in the normal uroepithelium cell line SV-HUC-1 (P < 0.01), although miR-155 expression in these cell lines varied." (PMID 25965824, 2015). "The expression of DMTF1 was decreased in bladder cancer tissues." (PMID 25965824, 2015). "In present report, the tumor suppressive role of DMTF1 was studied and confirmed in bladder cancer." (PMID 25965824, 2015).
B cell lymphomas (2 papers, 2017 to 2026). "This notion is further supported by the observation that MYC-induced B-cell lymphomas dramatically reduced the time of latency at either a DMTF1(−/−) or DMTF1(+/−) genetic background." (PMID 28257090, 2017).
breast tumor (1 paper, 2017). "Based on the alternative splicing sites of DMTF1 pre-mRNA, we designed PCR primers to specifically detect alternative DMTF1 splicing events and generated a DMTF1β-specific antibody to analyze breast tumor samples." (PMID 28257090, 2017).
colorectal cancer (1 paper, 2021). A primary or metastatic malignant neoplasm that affects the colon or rectum. "Furthermore, miR-675-3p was shown to target the DMTF1 3′-UTR in colorectal cancer and to thereby promote enhanced tumor cell proliferation." (PMID 33400243, 2021).
malignant lymphomas (1 paper, 2017). "Additional studies revealed that DMTF1-null mice developed spontaneous malignant lymphomas and deceased from various cancers at two years of age." (PMID 28257090, 2017). "Lymphomas could also arise from DMTF1(+/−) mice, suggesting that DMTF1 is haplo-insufficient for tumor suppression." (PMID 28257090, 2017).
melanoma (1 paper, 2026). A malignant, usually aggressive tumor composed of atypical, neoplastic melanocytes. "While Arid2 loss can result in genomic redistribution of BAF in melanoma, this is unlikely to occur in DMTF1 KD NSC given that DMTF1 loss down-regulates both Ss18 and Arid2 expression." (PMID 41481722, 2026).
cancer (13 papers, 2008 to 2026). A tumor composed of atypical neoplastic, often pleomorphic cells that invade other tissues. "KIAA0090, ATAD3B, TRIM27 and DMTF1, regulated by hypo-methylated sites, were also associated with cancer." (PMID 33549049, 2021). "In conclusion, we identified a novel function for the alternatively spliced DMTF1 gene product in autophagy-dependent cancer cell motility." (PMID 42187319, 2026). "Contrary to its proposed role as a tumor suppressor in cancer, we provide compelling evidence that DMTF1 acts to promote mouse and human NSC proliferation in vitro." (PMID 41481722, 2026). "In this review, we introduce general aberrant pre-mRNA splicing in cancers and discuss its therapeutic application using our recent discovery of the oncogenic DMTF1 isoform as an example." (PMID 28257090, 2017). "The presence of different isoforms of DMTF1, as well as other cancer-related regulators, provides insights about new vulnerable targets in cancer therapies." (PMID 28257090, 2017). "The altered expression of DMTF1 proteins was highly related to the pathophysiology of cancer." (PMID 32802855, 2020). "As an example, the gene locus of DMTF1 (cyclin D-binding myb-like transcription factor 1), also known as DMP1 (cyclin D-binding myb-like protein 1), encodes three major isoforms with different functions in cancers." (PMID 28257090, 2017). "It should be noted that miR-155 has many cancer-related targets, such as P85α and DMTF1." (PMID 27602769, 2016). "DMTF1 (or DMP1) is a transcription factor that harbors both cyclin D binding (CDB) and Myb-like (Myb) domains and thought to act as a tumor suppressor in certain cancer types." (PMID 41481722, 2026). "In addition to 4 same genes (KIAA0090, ATAD3B, TRIM27 and DMTF1) with LUSC-C1, ACP1 and SH3YL1 also played important roles in cancer." (PMID 33549049, 2021). "Thus, it is tempting to speculate a potential convergence of DMTF1 in both telomerase and ALT mechanisms, which may have important implications in aging and cancer research." (PMID 41481722, 2026).
tumor (13 papers, 2008 to 2026). "Only one of 40 DMTF1 null mice spontaneously developed a tumor in the first year of life, indicating that DMTF1 deficiency alone is insufficient to initiate tumorigenesis." (PMID 41481722, 2026). "The cyclin D binding Myb-like Transcription Factor 1 (DMTF1) is a haploinsufficient tumor suppressor in various tumors." (PMID 42187319, 2026). "In this report, two new and C-terminal-short DMTF1 isoforms, designated as DMTF1β and γ, were discovered, and the longer tumor suppressor isoform was accordingly named DMTF1α." (PMID 28257090, 2017). "Additional evidence for a tumor suppressive role of DMTF1 includes that the DMTF1 promoter can be activated by oncogenes RAS and HER2 but repressed by E2Fs and NFKB signals." (PMID 28257090, 2017). "Human DMTF1 cyclin D binding Myb-like transcription factor 1 is involved in tumor suppression and induction of apoptosis." (PMID 27282827, 2016). "DMTF1, also known as cyclin D-binding myb-like protein-1 (Dmp1), is a well accepted tumor suppressor." (PMID 25965824, 2015). "Among all predicted targets of miR-155, DMTF1 caught our attentions for its tumor suppressive role to induce cell cycle arrest." (PMID 25965824, 2015). "DMTF1 functions as a tumor suppressor inducing cell growth arrest or apoptosis." (PMID 34973136, 2023). "Interestingly, some of them function as tumor suppressors (e.g. BCL2L11, MXD1, WWOX, BNIP3L, and DMTF1) or are candidate tumor suppressors having anti-proliferative properties and DNA repair abilities (e.g. LRRC2, RPA4, PPP6R1, SPEN, RAP1GAP and CISH) (see discussion section)." (PMID 26918450, 2016).
DMTF1 also shares sentences with these, for which no sentence is quoted: non-small cell lung carcinoma (2 papers); acute myeloid leukemia (1); Burkitt lymphoma (1); Fanconi anemia (1); gastric cancer (1); glioblastoma (1); glioma (1); myelodysplastic syndrome (1); myeloma (1); osteosarcoma (1).